IRS2 (insulin receptor substrate 2)
Diseases named in the same sentence as IRS2 in open-access papers (continued):
Sharing a sentence is not in itself a finding about the gene and the disease.
Hyperinsulinemia (continued). "In contrast, in the PV zone, where Irs1 is abundantly expressed, insulin signalling is rather enhanced in the presence of hyperinsulinemia despite the downregulation of Irs2, resulting in the increased lipogenesis and development of steatosis." (PMID 27708333, 2016). "On a high fat diet, both IRS2+/−ApoE−/− and IRS2−/−ApoE−/− mice display glucose intolerance, hyperinsulinemia, and increased aortic lesion development when compared to IRS2+/+ApoE−/−, but unchanged plasma lipid levels." (PMID 25785279, 2015). "Ultimately, the sums of all of these processes appear to be mediated via an imbalance of insulin substrates, where hypoinsulinemia is characterized by excessive IRS-2 signaling, and hyperinsulinemia with predominant IRS-1 signaling." (PMID 22745692, 2012). "Based on the ChIP-seq data, the same FOXO1 feedback loop influencing Igf1r, Insr, Irs1, and Irs2 may be present in other tissues experiencing hyperinsulinemia conditions." (PMID 40105689, 2025). "Fat mass was increased in Irs2–/–; Cdk4-R24C mice, although this could have been secondary to hyperinsulinemia." (PMID 37712417, 2023). "In addition, we assessed the expression of Irs2, which had a larger fold change than Insr and was one of the most significantly altered genes upon hyperinsulinemia and starvation." (PMID 34921686, 2022). "Thus, it has been shown that a downregulation of IRS2 by hyperinsulinemia-mediated signaling impaired the polarization of macrophages by the IL-4/IRS2/Akt pathway due to the stabilization of a FoxO1-dependent corepressor complex." (PMID 35955975, 2022). "Hyperinsulinemia also results in a downregulation of endogenous IRS2 in macrophages." (PMID 35955975, 2022). "Therefore, the downregulation of IRS2 by hyperinsulinemia lowered tumor invasion and metastasis in the present study, which has also been proven in an obese and diabetic mouse model." (PMID 33690729, 2021). "Studies have shown that IRS2 may inhibit hyperglycemia and hyperinsulinemia, while promoting endogenous glucose production and glycogen synthesis." (PMID 32273844, 2020). "Moreover, the reduction of macrophage Irs2 expression is mediated by hyperinsulinemia via the insulin receptor (IR)." (PMID 30451856, 2018). "IRS2-knockout mice displayed hyperglycemia and hyperinsulinemia." (PMID 30003110, 2018). "Ten-week-old IRS2-KO mice displayed fasting hyperglycemia and hyperinsulinemia." (PMID 30003110, 2018). "Thus, in the PP zone, where Irs1 is less abundantly expressed and Irs2 expression is downregulated, insulin signalling is impaired despite the hyperinsulinemia, leading to the impaired suppression of gluconeogenesis and hyperglycaemia." (PMID 27708333, 2016). "Similarly, our results on elevated insulin levels in female diabetic rats may suggest that the decreased IRS-2 expression observed in the aorta could be in part due to hyperinsulinemia in this group." (PMID 34366875, 2021). "Sustained hyperinsulinemia and hyperglycemia with compromised insulin/IRS2/FOXO1 signaling yields high expression of MTP and apoC-III with an overproduction of TG-VLDL1 yet causes of compromised insulin/IRS2/FOXO1 signaling remain unclear." (PMID 28550272, 2018). "Hyperinsulinemia induced IGF1 resistance, accompanied by reduced IGF1R protein, as well as Igf1r and Irs2 mRNA expression via over-activation of phosphoinositide 3-kinase/forkhead box O1 (PI3K-FOXO1) signaling." (PMID 40105689, 2025). "Hyperinsulinemia has been reported to stimulate lipogenesis by activating SREBP, a process that inhibits IRS‐2 (Insulin receptor substrate 2) mediated insulin effects on glucose production." (PMID 37701187, 2023). "Hyperinsulinemia can reduce intracellular levels of IRS1 and IRS2 genes in cell culture models and mouse tissues." (PMID 36589630, 2022).
Hyperinsulinemia (continued). "In agreement with hyperinsulinemia in HFD mice, elevated expressions of IR, insulin receptor substrate 2 (IRS-2), phosphoinositide 3-kinase (PI3K), phosphoinositide-dependent kinase-1 (PDK1), and PPARγ were identified across 24 weeks of feeding." (PMID 33817571, 2021). "The actions of 2 and 5 FATP are dose-dependent and bimodal, and they are mediated by insulin receptor substrate-2 (IRS-2) under low concentrations of insulin and insulin receptor substrate-1 (IRS-1) during states of hyperinsulinemia." (PMID 25789328, 2015). "Importantly, this study uncovered that hyperinsulinemia induces IGF1 resistance in hypothalamic neurons by downregulating IGF1R and IRS2 through the PI3K-FOXO1 signaling pathway." (PMID 40105689, 2025). "In contrast, the hepatic insulin signaling in the Irs1−/− mice fed the HF diet was impaired, since Irs1 was absent and Irs2 signaling was suppressed by the hyperinsulinemia induced by the HF diet." (PMID 24284392, 2013). "Thus, although insulin levels were elevated in fasted conditions in IRS-2(−/−) mice, expression of mRNAs coding for GK and GKRP was reduced, since in this model moderate hyperinsulinemia cannot compensate for the presence of severe hepatic insulin resistance." (PMID 23560040, 2013). "Although insulin and leptin bind to separate receptors in the neurons of the VMH and VTA, they share the same signaling cascade, called insulin receptor substrate-2 (IRS2)/phosphatidyl inositol-3-kinase (PI3K) and thus hyperinsulinemia may block leptin signaling." (PMID 40950761, 2025). "Further note, unlike IRS‐1/PI3K, activation of IRS‐2 and IRS‐2/PI3K in both muscle and liver is resistant to downregulation in DIO/MetS/T2DM17, 18, 19, 20 and is responsive to hyperinsulinemia." (PMID 34766133, 2021).
Hyperglycemia (47 papers, 2008 to 2026). An increased concentration of glucose in the blood. "It should be noted that while hyperglycemia-mediated effects of IRS2 deficiency cannot be fully excluded, these effects are relevant to PVAT dysfunction in DM2." (PMID 29628894, 2018). "The deletion of both IRS1 and insulin receptor substrate 2 (IRS2) (H-DKO mice: heart-specific IRS1 and IRS2 double gene knock-out) in the brain and liver causes hyperglycemia, but such deficiencies in the pancreas and heart cause organ failure." (PMID 29484207, 2018). "Chronic hyperglycemia in Irs-2−/− mouse may cause the elevation in Fbln5 in the islets at the basal state." (PMID 28539593, 2017). "Chronic hyperglycemia in IRS2-null mice may contribute to dedifferentiation via oxidative stress or glucotoxicity, but it is likely not the only cause, since Pdx1 expression is reduced before the onset of hyperglycemia." (PMID 37712417, 2023). "Our findings illustrated that ZnO NPs (Z1) alleviated hyperglycemia, cleared amyloid-β accumulation, maintained neural integrity, lessened fat deposition in the liver, and altered the expression of irs2, pi3k, ager, and app genes." (PMID 42255438, 2026). "In the kidney, impairment of IRS1-dependent inhibition of gluconeogenesis in the proximal tubule contributes to hyperglycemia, whereas IRS2-dependent signaling remains intact." (PMID 40725728, 2025). "Mice with complete deletion of hepatic IRS2 develop hyperglycemia, impaired hepatic insulin signaling, and elevated gluconeogenesis." (PMID 38596462, 2024). "Studies have shown that IRS2-null mice exhibit glucose intolerance and IR, and develop symptoms of hyperglycemia." (PMID 36860209, 2023). "Depletion of CREB activity in pancreatic β-cells leads to hyperglycemia due in part to diminished expression of IRS-2, excessive β-cell apoptosis and decreases in insulin secretion." (PMID 35308228, 2022). ", indicating that no significant glycogen stores were present in these conditions, despite hyperglycemia in IRS2-KO mice." (PMID 30003110, 2018). "IRS2−/− mice had higher non-fasting levels of plasma insulin (9 ± 1 vs. 20 ± 2 μU/ml, p < 0.01) and exhibited fasting hyperglycemia (5.3 ± 0.57 vs. 12.6 ± 2.7 mMol/l, p < 0.05) than IRS2+/+." (PMID 29628894, 2018). "Further, it was suggested that a sufficiently high level of IRS-2 expression in the liver during fasting state (i.e. between meals) is important in suppressing postprandial hyperglycemia." (PMID 29089472, 2017). "Reduced levels of IRS2 in humans have been proposed to lead to desensitized insulin/cytokine signalling and thus to hyperglycemia/muted immune responses, with prolonged IRS2 deficits exacerbating islet cell mass reduction leading to T2DM." (PMID 26178806, 2015). "The fertility of Irs2 null males was comparable to wild-type males until the onset of hyperglycemia when reproductive capacity declined drastically." (PMID 23741292, 2013). "Selective loss of GSK-3β in skeletal muscle improves glucose tolerance and insulin signaling, while removal of this isoform in β-islet cells can reduce hyperglycaemia in diabetic IRS-2 KO mice." (PMID 21253590, 2011). "The hyperglycemia stimulates the phosphorylation of IRS2 on serine and threonine and this phosphorylation appears to target the protein for degradation by the proteasome, as proteasome inhibitors block this degradation." (PMID 19007436, 2008). "It is also possible that hyperglycemia itself is a major driver of β-cell proliferation under these conditions, through Irs2-Creb signaling that may bypass Insr/Igf1r18." (PMID 35136059, 2022). "Under hyperglycemia, we found sustained phosphorylation of IRS2 in all three cell lines." (PMID 24260287, 2013). "Pancreatic deletion of the same isoform alleviated hyperglycaemia in IRS-2 KO mice." (PMID 21253590, 2011). "It remains to be shown whether impaired IRS2 or IRS1 signaling in response to hyperglycemia and possibly to FFAs is mediated through induction of ER stress in β-cells." (PMID 19305497, 2009).
Hyperglycemia (continued). "Thus, suboptimal level of IRS-2 expression, often observed under hyperinsulin-secretion conditions (e.g. obesity or taking snacks besides meals), was thought to be a contributing factor to postprandial hyperglycemia." (PMID 29089472, 2017). "In the PT, IRS2-dependent stimulation of sodium reabsorption could cause hypertension and edema, while impaired IRS1-dependent signaling could induce unsuppressed gluconeogenesis, possibly contributing to hyperglycemia." (PMID 27247938, 2016). "On the basis of these findings, we hypothesized that under the HF condition where the expression of Irs2 is downregulated, deletion of Irs1 leads to impaired insulin signalling in both the PP and PV zones, resulting in hyperglycaemia and suppression of steatosis." (PMID 27708333, 2016). "Thus, chronic hyperglycemia could employ this mechanism to decrease IRS2 and induce β-cell apoptosis." (PMID 19007436, 2008). "Inhibiting the expression of miR-135a in C2C12 myoblasts can increase the expression levels of IRS2 and Akt in C2C12 myoblasts, improve glucose tolerance, and reduce the symptoms of hyperglycemia." (PMID 36860209, 2023). "The inhibition of insulin receptor substrate 2 (IRS2) and insulin receptor (INSR) was predicted to activate hyperglycemia and CVD." (PMID 37569355, 2023). "Mice with liver-specific double IRS1 and IRS2 knockout exhibit severe hyperglycemia, suggesting that hepatic IRS1 and IRS2 are the critical mediators of insulin’s regulation of glucose metabolism." (PMID 35074429, 2022). "Mice with liver-specific double IRS1 and IRS2 knockout exhibit severe hyperglycemia, suggesting that liver IRS1 and IRS2 are the critical mediators of insulin’s regulation of glucose metabolism." (PMID 33672754, 2021). "At the same time, in a model of hepatic PHD3 deletion, HIF2-α increased the expression of insulin receptor substrate 2 (IRS2), ameliorated hyperglycaemia and regulated hepatic glucose metabolism." (PMID 32816039, 2020). "Pancreatic β-cell malfunction is characterized by the lack of insulin production and secretion to regulate glucose metabolism, which results in hyperglycemia in PDX-1 knockout mice and IRS-2 knockout mice." (PMID 31627434, 2019). "Hyperglycemia promotes AGEs production, which inhibit tyrosine phosphorylation of IRS-1 and IRS-2 and decrease activation of the PI3-K/Akt pathway by activation of phosphokinase C (PKC)." (PMID 27413253, 2016). "One intriguing substrate is IRS2, which is required for β-cell survival and is degraded in the INS1 (INS-1) β-cell line upon chronic exposure to hyperglycemia or IGF1." (PMID 19007436, 2008). "TNF-α activates the NF-κβ intracellular signaling cascade, which inhibits the phosphorylation of insulin receptor substrate 2 (IRS-2), serine/threonine kinase or protein kinase B (AKT/PKβ), glucose transporter 2, and glucose transporter 4, culminating in IR and hyperglycemia." (PMID 41155165, 2025). "Experimental validation proved that mSMG ameliorated hyperglycemia, IR, and TNF-α, enhanced glucose consumption and glycogen synthesis, relieved the phosphorylation of JNK1 and IRS-2 (Ser388), and elevated the phosphorylation of Akt (Ser473) and GSK-3β (Ser9) and GLUT2 expression in KK-Ay mice." (PMID 39285464, 2024). "Mice lacking insulin receptor substrate-2 (IRS-2) in the liver developed severe IR and hyperglycemia." (PMID 31920677, 2019). "Animals without IRS-2 exhibited insulin resistance with fasting hyperglycemia, due to inadequate insulin production, which in final resulted in diabetes, which was worse than lack of IRS-1." (PMID 27413253, 2016). "Testicular weight was reduced similarly in non-diabetic and diabetic Irs2−/− mice, indicating that hyperglycemia does not compound the effects of Irs2 deletion on impaired testis development." (PMID 23741292, 2013). "NesCreIrs2KO mice therefore permit the investigation of the role of IRS-2 signalling in neurons in the absence of some confounding factors such as systemic hyperglycemia." (PMID 22383997, 2012).
Hyperglycemia (continued). "To study neuronal function and synaptic plasticity in the absence of confounding factors such as hyperglycaemia, we used a mouse model with a central nervous system- (CNS)-restricted deletion of IRS-2 (NesCreIrs2KO)." (PMID 22383997, 2012). "However, no glycogen-storing cells were detected in the kidney from diabetic IRS2-KO mice, indicating that hyperglycemia itself is not enough to promote renal glycogen synthesis." (PMID 30003110, 2018). "A similar result was found in another experiment that involved IRS1 knockout mice lacking hepatic IRS2, it was observed that leptin, IGF1 levels was decreased, glucose tolerance ability was impaired and resulted in hyperglycemia." (PMID 35241081, 2022). "Taken together, these findings in tissue-specific cells show that hyperglycemia converges on major insulin, lipid, and fibrosis pathways by DNA methylation to regulate the expression of core genes that consist of but are unlikely to be limited to MTOR, RPTOR, IRS2, TXNRD1, LCAT, SMPD3, and COL1A2." (PMID 36633903, 2023).
Glucose intolerance (21 papers, 2012 to 2025). Glucose intolerance (GI) can be defined as dysglycemia that comprises both prediabetes and diabetes. "As for glucose homeostasis, old male SA/SA mice showed mild glucose intolerance that was associated with reduced expression of IRS2 in the liver." (PMID 40238664, 2025). "Since homozygous Cdk4-R24C alleles rescued glucose intolerance in male mice by correcting insulin deficiency, we predicted that β cell function, mass, or both were restored in Irs2–/–;Cdk4-R24C/R24C mice." (PMID 37712417, 2023). "Diseases associated with disrupted functions of IRS2 include fatty liver disease and glucose intolerance, which is a precursor to MetS." (PMID 25806089, 2015). "In IRS2-/- mice, on the other hand, elevation of blood glucose emerges when they become about 10-week old, along with marked glucose intolerance." (PMID 33270683, 2020). "Further studies are required to determine whether the reduced hepatic IRS2 level is sufficient to explain glucose intolerance or other mechanisms exist for the dysregulation of glucose homeostasis in aged SA/SA male mice." (PMID 40238664, 2025). "Here, we report that replacing both alleles of Cdk4 with Cdk4-R24C rescued glucose intolerance in IRS2-null mice without improving insulin sensitivity." (PMID 37712417, 2023). "IRS2 knockdown worsened both basal and Dex-induced glucose intolerance." (PMID 37253782, 2023). "Moreover, mice with deletion of the Irs2 gene specifically into pancreatic beta-cells develop glucose intolerance, and reduced beta-cell mass." (PMID 22563476, 2012). "However, SA/SA male mice showed decreased IRS2 expression in the liver, which may explain glucose intolerance in SA/SA male mice." (PMID 40238664, 2025). "However, old SA/SA mice showed decreased IRS2 expression in the liver, which may contribute to glucose intolerance in SA/SA male mice." (PMID 40238664, 2025). "Furthermore, the impairment of β-cell growth and overt glucose intolerance shownin a β-cell-specific IR knockout (βIRKO) mouse or an IRS-2 null mouse are relevant to AKT-mediated anti-apoptotic and proliferative mechanisms regardless the involvement of Wnt signaling." (PMID 23874448, 2013). "DCI administration decreased FBS, improved glucose intolerance through PI3K/AKT pathway, namely by upregulating insulin receptor substrate (IRS) and PI3Kp85 as well as IRS‐2 and AKT phosphorylation." (PMID 39479697, 2024). "Furthermore, overexpression of SOCS3 decreased the hepatic expressions of IRS1, IRS2 and PI3K, and resulted in glucose intolerance and decrease glucose uptake." (PMID 29743495, 2018). "In contrast, studies on glucose intolerance and IGF-1 have been conducted using knockout mice lacking the insulin receptor substrate 2 (IRS2) gene." (PMID 33746806, 2021).